CCND2 (cyclin D2)
Diseases named in the same sentence as CCND2 in open-access papers (continued):
Sharing a sentence is not in itself a finding about the gene and the disease.
liver cancer (8 papers, 2013 to 2023). An epithelial or non-epithelial malignant neoplasm that arises from the liver. "Surprisingly, low CCND2 expression in liver cancer was also associated with a poor prognosis." (PMID 30308939, 2018). "In addition, the in vitro expression of miR-26 in liver cancer cells induced cell-cycle arrest associated with direct targeting of cyclin D2." (PMID 26057471, 2015). "CCND2 is dysregulated in various tumors and is correlated to patient prognosis, including lung, breast, and liver cancers." (PMID 37628967, 2023). "Low CCND2 expression was infrequent in liver cancer, possibly because other mechanisms interfered with CCND2 mRNA expression." (PMID 30308939, 2018). "Aberrantly methylated CCND2 has been reported in breast, lung, gastric, and liver cancers." (PMID 30308939, 2018). "Using TargetScan and miRanda database, we found that the potential predicated target genes of miR-646 consist of methylthioadenosine phosphorylase (MTAP), WEE1 G2 checkpoint kinase (WEE1), and cyclin D2 (CCND2), which are involved in the development of liver cancer." (PMID 25177719, 2014). "Thus, CCND2 might also provide a new treatment target for inducer drugs for liver cancer patients." (PMID 30308939, 2018).
megalencephaly (8 papers, 2017 to 2024). A congenital abnormality in which the occipitofrontal circumference is greater than two standard deviations above the mean for a given age. "Some cases of megalencephaly and polymicrogyria are caused by mutations in CCND2 (cyclin D2), a protein implicated in the cell cycle progression and a target of GSK3." (PMID 35069108, 2021). "Recently disease-causing gain-of-function mutations in the CCND2 gene was identified in patients with megalencephaly-polymicrogyria-polydactyly-hydrocephalus syndrome-3 (MPPH3; MIM 615938)." (PMID 33613193, 2021). "CCND2 GoF variants have been associated with megalencephaly-polymicrogyria-polydactyly-hydrocephalus syndrome 3 (MPPH3, OMIM#615938), a developmental brain disorder characterized by megalencephaly, bilateral perisylvian polymicrogyria, and postaxial polydactyly." (PMID 38884091, 2024). "The mutated form of CCND2 present in MPPH patients induces a gain-of-function mutation of cyclin D2, meaning it remains stabilized during neural progenitor cell proliferation, which result in uncontrolled cell growth, leading to megalencephaly exhibited in these patients." (PMID 33805800, 2021). "Thus, de novo mutations in CYCLIN D2—that produce a stable form of the protein—have been identified in individuals who have a rare overgrowth disorder named Megalencephaly-polymicrogyria-polydactyly-hydrocephalus syndrome (MPPH)." (PMID 31545166, 2019). "The phosphorylation and subsequent inactivation of CCND2 by GSK3-beta plays a key role in controlling CCND2 activity, and dysregulation of this interaction has been implicated in megalencephaly." (PMID 29170629, 2017). "Since CDK6 loss-of-function mutation causes microcephaly and cyclin D2 gain-of-function mutation results in megalencephaly there should not be a surprise that these two proteins form a heterodimer to obtain an active protein kinase." (PMID 33805800, 2021).
type 2 diabetes (8 papers, 2015 to 2025). "With regard to rs8108269 near GIPR and rs11063069 near CCND2, the association of the GIPR locus with type 2 diabetes was more significant in female in the original European study, whereas the effect of CCND2 locus was stronger in male." (PMID 25951451, 2015). "β cell failure in the IRS2-deletion mouse type 2 diabetes model is, in part, due to loss of CDK4 regulator cyclin D2." (PMID 37712417, 2023). "Sex differentiated analysis for the association of rs11063069 near CCND2 and rs8108269 near GIPR with type 2 diabetes." (PMID 25951451, 2015). "For seven of overall 17 potential target genes, we found studies reporting a role in CVD, comprising HF and cardiac remodeling after MI (Ccnd2, Pde1c, Ddah1), atherosclerosis (Igf1r), blood pressure and hypertension (Fign, Efnb3), and type 2 diabetes (Igf2bp2)." (PMID 35332188, 2022).
bladder cancer (7 papers, 2017 to 2024). "In bladder cancer, miR-194-5p targeting in combination with CCND2 significantly inhibits bladder tumour cell proliferation and promotes bladder tumour cell apoptosis." (PMID 34052838, 2021). "Evidence has shown that elevated expression of CCND2 contributed to CDDP resistance in bladder cancer cells." (PMID 34746018, 2021). "It was found that regulators of cell cycle and cell proliferation such as S100A4, CCND2, C13ORF15 (RGCC), and SYK and genes associated with glucose or ion transport such as SLC2A3 and TMEM16A (ANO1) were upregulated in the persistently infected bladder cancer cells." (PMID 34044804, 2021). "Previous studies have reported that CCND2 could influence CDDP resistance in bladder cancer." (PMID 34746018, 2021). "In the current analysis, identified CCND2 is unmethylated and resides on the CNV gain region in the tested bladder carcinoma datasets." (PMID 35845108, 2022).
chronic lymphocytic leukemia (7 papers, 2014 to 2024). "Compared with unaffected people, cyclin D2 exhibited over-expression in B-cell chronic lymphocytic leukemia cases and preferentially expressed in human T-lymphotropic virus type I (HTLV-I) infected T cell lines." (PMID 24743557, 2014). "Finally, we identify and validate the critical super-enhancer that regulates ectopic expression of CCND2 in a subset of patients with MM and in chronic lymphocytic leukemia." (PMID 34521827, 2021). "Finally, we explored the activity of the CCND2 super-enhancer in B cell chronic lymphocytic leukemia (CLL), the most common blood cancer." (PMID 34521827, 2021). "Cyclin D2 is overexpressed in cyclin-D1-negative MCL, chronic lymphocytic leukemia/small lymphocytic lymphoma, and DLBCL." (PMID 30755239, 2019). "Cyclin D2 translocation and overexpression are described in non-Hodgkins' lymphoma (NHL), CLL, B cell lymphocytic leukemia (BLL) and lymphoplasmacytic lymphomas (LPL)." (PMID 25914884, 2015).
germ cell tumor (7 papers, 2006 to 2024). A benign or malignant, gonadal or extragonadal neoplasm that originates from germ cells. "In particular, the CCND2 gene (encoding cyclin D2) resides on chromosome 12p that is frequently amplified and expressed at high levels in testicular germ cell tumors." (PMID 16762081, 2006). "KRAS, CDKN1B, CCND2, ETV6, and RAD52 mutations are the most common in germ cell tumors." (PMID 37958970, 2023). "The most prevalent changes in germ cell tumors are CDKN1B Amplification, KRAS Amplification, CCND2 Amplification, ETV6 Amplification, and RAD52 Amplification." (PMID 37958970, 2023). "Intriguingly, transplantation of SSCs overexpressing both CCND2 and CCNE1 produced tubules consisting of spermatogonial clusters and an absence of haploid cells, resembling germ cell tumours and similar to TAT tubules." (PMID 37564373, 2023).
Obesity (7 papers, 2018 to 2024). Accumulation of substantial excess body fat. "Given the effects of high dose tamoxifen upon PKC mitogenic signals, PKCζ must be considered a top candidate, as PKCζ signals are involved in obesity associated β-cell proliferation via mTOR and Cyclin-D2." (PMID 31490929, 2019). "Control of β-cell proliferation under stressful conditions in adults by the regulation of cyclin D2 (CCND2) expression is important for a compensatory increase in β-cell mass during obesity." (PMID 29606121, 2018). "In our previous study, we found that BCM and the number of islets is increased in mice fed HSTD for 22 weeks, which show obesity and hyperglycemia and hyperinsulinemia, and that the expression levels of cyclin D1 and cyclin D2 mRNA in islets are increased in these mice." (PMID 31083314, 2019). "Five variants were top weighted (above the threshold of 0.75) in more than one cluster: CDC123/CAMKID (Beta Cell and Proinsulin), HSD17B12 (Beta Cell and Obesity), ADCY5 (Beta Cell and Lipodystrophy), CCND2 (Proinsulin and Lipodystrophy), and HNF4A (Beta Cell and Proinsulin)." (PMID 30240442, 2018).
metastatic disease (6 papers, 2005 to 2025). "Likewise, LRPAP1, MSX1, CCND2, and NRP1 displayed strong associations with monocytes, Tregs and NK cells, especially in metastatic tumors." (PMID 40943183, 2025). "COL3A1, COL5A2, VCAN, CCND2, JAG2, and VTN showed consistent positive correlations with all three scores in both primary and metastatic tumors, suggesting their involvement in enhancing stromal support and recruiting immune cells." (PMID 40943183, 2025). "There were rare amplifications of the D-cyclin genes (CCND1, CCND2, and CCND3); interestingly, each of these events occurred in tumors from patients with metastatic disease." (PMID 32198354, 2020). "In our data, the most remarkable change in metastatic tumor was occurred at increases (≧1.30) of D1S1635 (1p36.22), D1S214 (1p36.31), EXT1 (8q24.11-q24), AFM137XA11 (9p11.2), CCND2 (12p13), 8 M16/SP6 (12ptel), IGH (D14S308), HIC1 (17p13.3), 282 M15/SP16 (17ptel), and LAMA3 (18q11.2)." (PMID 23199169, 2012). "This may suggest that the overexpression of cyclin D2, and not that of cyclins D1 and D3, is related to metastatic tumours." (PMID 16012517, 2005).
osteosarcoma (6 papers, 2014 to 2022). A usually aggressive malignant bone-forming mesenchymal neoplasm, predominantly affecting adolescents and young adults. "LncRNA KCNQ1OT1 functions as a competing endogenous RNA (ceRNA) for miR-4458, regulating the expression of CCND2 and enhancing the progression of osteosarcoma." (PMID 34015762, 2021). "LncRNA KCNQ1OT1 has been ascertained as a sponge of miR-4458, thus facilitating osteosarcoma cell growth via upregulating CCND2." (PMID 34863279, 2021). "For example, it has been reported that miR-2682-3p could inhibit osteosarcoma cell proliferation by targeting CCND2 (Cyclin D2), MMP8 (Matrix metallopeptidase 8), and Myd88 (Myeloid differentiation primary response gene 88)." (PMID 35733138, 2022). "Among these we analyzed CD133, N-Myc, CCND2, E2F1 and E2F2, Bcl-2 and IAP-2, since they are overexpressed in 3AB-OS cells and many of them were found to be frequently overexpressed in tissues of osteosarcoma patients." (PMID 25174983, 2014).
atherosclerosis (5 papers, 2020 to 2024). A disease characterized by the build-up of fatty material and calcium deposition in the arterial wall resulting in partial or complete occlusion of the arterial lumen. "Mechanistically, circRSF1 competitively targets miR-758 and positively regulates the expression of CCND2, indicating that circRSF1 could be a potential future target for atherosclerosis treatment." (PMID 37418054, 2024). "With respect to miR-652–3p, one report demonstrated that it could promote atherosclerosis by inhibiting endothelial repair gene Cyclin D2." (PMID 37228823, 2023). "However, promoted CCND2 expression and inhibition of miR‐652‐3p expression are conductive to endothelial cell repair in atherosclerosis, which is partially consistent with our findings regarding the CCND2." (PMID 32666704, 2020). "In addition, miR-652-3p inhibition and decreased atherosclerosis by promoting cyclin D2 expression." (PMID 35111226, 2022). "Mechanistic studies revealed that RNCR3 binds to miR-185-5p, regulates cyclin D2 expression, and promotes cell growth and cytokine secretion, which suggests that RNCR3 may be a potential target for atherosclerosis treatment." (PMID 37418054, 2024).
brain tumors (5 papers, 2005 to 2022). "By considering another profile, the highest expression in proliferating cell nuclear antigen (PCNA) and cyclin D2, and the lowest expression in cyclin E were observable in all types of brain tumors." (PMID 31565199, 2019).
Burkitt lymphoma (5 papers, 2003 to 2024). A rare form of malignant mature B-cell non-Hodgkin lymphoma. "With regard to EBV, the viral-encoded protein LMP-1 induces the expression of cyclin D2 to promote uncontrolled cell proliferation in EBV-positive Burkitt’s lymphoma cell lines." (PMID 35562811, 2022). "EBV infection or its transforming protein latent membrane protein 1 (LMP1) up-regulates Cyclin D2 expression in primary B-lymphocytes and Burkitt's lymphoma cells." (PMID 21347341, 2011).
cervical carcinoma (5 papers, 2018 to 2022). A carcinoma arising from either the exocervical squamous epithelium or the endocervical glandular epithelium. "This study aimed to explore the expression, function, and underlying mechanism of action of CCND2 AS1 in cervical cancer." (PMID 32607313, 2020). "Using the qRT-PCR assay, we detected higher CCND2 expression in cervical cancer cells than normal Ect1/E6E7 cells." (PMID 34746018, 2021). "Significant up-regulation of CCND2 was observed in cervical cancer samples when compared with adjacent normal samples." (PMID 34746018, 2021). "Our qRT-PCR and luciferase reporter assays showed that Cyclin D2 (CCND2) was the direct target for miR-206 in cervical cancer cells." (PMID 34746018, 2021). "In cervical cancer tissues, the expression of OTUD6B-AS1 was negatively correlated with the expression of miR-206, but was positively associated with the level of CCND2." (PMID 34746018, 2021). "Here, we showed for the time that suppression of CCND2 decreased CDDP resistance in cervical cancer cells." (PMID 34746018, 2021). "This study is the first to report that CCND2 was a direct downstream target of miR-206 in CDDP-resistant cervical cancer cells." (PMID 34746018, 2021). "Cyclin D2 (CCND2) is expressed in a broad range of tumor types, and it has key roles in the carcinogenesis and progression of cervical cancer." (PMID 34746018, 2021). "Next, we explored the associations between CCND2 AS1 expression and patient clinicopathological characteristics in the 46 cervical cancer patients." (PMID 32607313, 2020). "Methylation-specific PCR (MSP) and bisulfite genomic sequencing (BGS) were used to detect CCND2 AS1 promoter methylation status in cervical cancer cells." (PMID 32607313, 2020). "Consistent with our qRT-PCR results, we found that CCND2 AS1 was significantly lower in the cervical cancer tissues compared with the 13 normal tissues (p < 0.05)." (PMID 32607313, 2020). "We found that decreased expression of CCND2 AS1 was associated with patient age and tumor size, and forced overexpression CCND2 AS1 inhibited cervical cancer cell proliferation in vitro and in vivo, at least partly by arresting the cells at the G1/S phase." (PMID 32607313, 2020). "CCND2 AS1 expression was elevated after treatment of cervical cancer cells with the DNA methyltransferase inhibitor 5′-azacytidine (5′-Aza), and this was mediated, at least in part, via reduced CpG methylation at the CCND2 AS1 promoter." (PMID 32607313, 2020). "Decreased CCND2 AS1 expression correlated with patient age and tumor size, pointing to a potential role for CCND2 AS1 in cervical cancer cell growth." (PMID 32607313, 2020). "CCND2 AS1 expression is downregulated in cervical cancer, potentially through increased CCND2 AS1 promoter methylation, and the upregulation of CCND2 AS1 expression inhibited tumor growth." (PMID 32607313, 2020). "To investigate the functions of CCND2 AS1, we overexpressed or knocked down CCND2 AS1 in the human cervical cancer cell lines HeLa and SiHa, both of which express very low endogenous levels of CCND2 AS1." (PMID 32607313, 2020). "CCND2 AS1 expression was lower in cervical cancer compared with normal cervical tissues, and the level was significantly correlated with the patient age and tumor size." (PMID 32607313, 2020). "In this study, we show for the first time that lncRNA CCND2 AS1 expression is downregulated in cervical cancer tissue compared with adjacent normal tissue." (PMID 32607313, 2020). "We found that CCND2 AS1 levels were significantly lower in the cervical cancer tissues compared with the normal tissues (p < 0.05)." (PMID 32607313, 2020). "Low CCND2 AS1 expression was significantly associated with patient age (p = 0.029) and tumor size (p = 0.033), suggesting a potential role for CCND2 AS1 in cervical cancer growth." (PMID 32607313, 2020).